ZFPM2 (zinc finger protein, FOG family member 2)
Description:
Transcription regulator that plays a central role in heart morphogenesis and development of coronary vessels from epicardium, by regulating genes that are essential during cardiogenesis. Essential cofactor that acts via the formation of a heterodimer with transcription factors of the GATA family GATA4, GATA5 and GATA6. Such heterodimer can both activate or repress transcriptional activity, depending on the cell and promoter context. Also required in gonadal differentiation, possibly be regulating expression of SRY. Probably acts a corepressor of NR2F2 (By similarity).
Synonyms: hFOG-2; FOG2; ZNF89B; PRDM19; DIH3; SRXY9; ZC2HC11B
Tractability: PROTAC: UniProt records ubiquitination sites on it.
Gene: Protein-coding gene on chromosome 8 (104,590,733 to 105,804,539, forward strand). Ensembl gene ENSG00000169946.
Subcellular location: Nucleus
Subcellular location (Human Protein Atlas): Nucleoplasm
Pathways (Reactome):
Developmental Biology: Transcriptional regulation of testis differentiation
Hemostasis: Factors involved in megakaryocyte development and platelet production
Gene Ontology:
Molecular function: protein binding; RNA polymerase II-specific DNA-binding transcription factor binding; transcription coactivator activity; transcription corepressor activity; zinc ion binding
Biological process: fat cell differentiation; negative regulation of DNA-templated transcription; negative regulation of transcription by RNA polymerase II; outflow tract septum morphogenesis; positive regulation of transcription by RNA polymerase II; right ventricular cardiac muscle tissue morphogenesis; ventricular septum morphogenesis; cell differentiation; heart development; positive regulation of cardiac muscle cell proliferation; cardiac muscle tissue morphogenesis; negative regulation of fat cell differentiation; negative regulation of female gonad development; outflow tract morphogenesis; positive regulation of DNA-templated transcription; positive regulation of male gonad development; regulation of transcription by RNA polymerase II
Cellular component: nucleoplasm; chromatin; nucleus; cytoplasm
Genetic constraint (gnomAD): Loss-of-function variants: 17 observed, 92.94 expected, observed/expected ratio (o/e) 0.18, 90% interval 0.12 to 0.27. The upper end of that interval is the gene's LOEUF score, 0.27, which puts it in group 1 of 6, group 1 being the genes least tolerant of losing a copy. Missense variants: 1,296 observed, 1,436.2 expected, observed/expected ratio (o/e) 0.9, 90% interval 0.86 to 0.94. Synonymous variants: 517 observed, 521.44 expected, observed/expected ratio (o/e) 0.99, 90% interval 0.92 to 1.07.
Homologues: Orthologues: chimpanzee ZFPM2 (99% identical), macaque ZFPM2 (98% identical), dog ZFPM2 (96% identical), rabbit ZFPM2 (96% identical), pig ZFPM2 (95% identical), rat Zfpm2 (94% identical), mouse Zfpm2 (94% identical), guinea pig ZFPM2 (79% identical), tropical clawed frog zfpm2 (77% identical), zebrafish zfpm2a (63% identical), Drosophila melanogaster ush (18% identical). Paralogues in human: ZFPM1 (28% identical).
Diseases named in the same sentence as ZFPM2 in open-access papers:
ZFPM2 is named in the same sentence as 86 diseases in open-access papers, as found by Europe PMC text mining. Sharing a sentence is not in itself a finding about the gene and the disease. The quoted sentences say what the papers report.
congenital heart disease (7 papers, 2014 to 2021). A heart disease that is present at birth. "In humans, mutations in ZFPM2 have commonly been shown to be associated with congenital heart disease but only recently have heterozygous and homozygous missense variants been detected in individuals with isolated 46,XY PGD and CGD." (PMID 27899157, 2016). "ZFPM2 displayed a very high association score with tetralogy of Fallot (TOF), which is the most common form of congenital heart disease." (PMID 34946866, 2021). "Three ZFPM2 variants found in our study had been previously reported as pathogenic variants in congenital heart disease, although they have not been reported to be associated with genital anomalies." (PMID 27899157, 2016). "About half of the ZFPM2 variants we identified have not been previously reported, while the other five variants have been reported in ClinVar in association with congenital heart defects (TOF; MIM# 187500), diaphragmatic hernia (DIH3; MIM# 610187), or 46, XY DSD (SRXY9; MIM# 616067)." (PMID 31962012, 2020). "A large proportion of these variants were previously reported in association with congenital heart defects (CHD) but a lack of supporting evidence led us to classify many of these GATA4 and ZFPM2 variants as variants of unknown significance (VUS)." (PMID 31962012, 2020).
Tetralogy of Fallot (6 papers, 2007 to 2024). A congenital cardiac malformation comprising pulmonary stenosis, overriding aorta, ventricular septum defect, and right ventricular hypertrophy. "ZFPM2 variants were found in three patients with cardiac malformations and had previously been associated with tetralogy of Fallot, a conotruncal heart defect commonly observed in patients with 22q11.2DS." (PMID 38586596, 2024). "Mutations in NKX2-5 (5q35.1), GATA4 (8q23.1), ZFPM2 (8q23.1), GATA6 (18q11.2), GDF1 (19p13.11), JAG1 (20p12.2), and TBX1 (22q11.21) have been reported in sporadic cases with tetralogy of Fallot; however, interaction of these genes and FMR1 gene has never been reported." (PMID 28751920, 2017). "In this report, we screened a larger CTD population, which comprised 145 tetralogy of Fallot (TOF), 37 double-outlet ventricle outflow (DORV), and 18 transposition of the great artery (TGA), to investigate exon mutations as well as copy number variations in ZFPM2/FOG2." (PMID 25025186, 2014). "Intriguingly, we found DMR in ZFPM2 which is a gene highly related to Tetralogy of Fallot (TOF) in the DisGeNET database and ZFPM2 promoter hypermethylation has been found in TOF patients." (PMID 34946866, 2021). "A mutation (p.Glu216Asp) in the N-terminal zinc finger was detected in 2/26 patients with Tetralogy of Fallot (TOF), and this mutation resulted in reduced transcriptional activity without affecting GATA4's ability to bind DNA, nor its interaction with ZFPM2 (FOG2)." (PMID 17592645, 2007).
congenital diaphragmatic hernia (4 papers, 2005 to 2022). A posterolateral defect of the diaphragm that allows passage of abdominal viscera into the thorax, leading to respiratory insufficiency and persistent pulmonary hypertension with high mortality. "Haploinsufficiency of ZFPM2 is associated with congenital diaphragmatic hernia (CDH) as well as congenital heart defects (CHD), both consistent features of PKS." (PMID 25329894, 2014). "As damaging variants in these genes cause congenital diaphragmatic hernia, these data imply that GATA6 haploinsufficiency causes diaphragmatic dysgenesis by disrupting NR2F2 and ZFPM2 gene programs." (PMID 33054971, 2020).
malignant pleural mesothelioma (4 papers, 2020 to 2025). A malignant neoplasm that arises from mesothelial cells in the pleura and shows a diffuse growth pattern. "The ZFPM2 protein, also named Fog2, was identified as a biomarker of malignant pleural mesothelioma and has been associated with ovarian tumours and neuroblastoma." (PMID 34439758, 2021). "In miRNA-targeted genes of READ, ZFPM2 was recommended as a diagnostic biomarker for malignant pleural mesothelioma and PLXNA1 and PTPRU were related to lung cancer or colon cancer." (PMID 32964043, 2020).
neuroblastoma (4 papers, 2009 to 2021). Neuroblastoma (NB) is the most common solid, extracranial childhood tumor. "Abnormal expression of ZFPM2 in ovarian tumors and neuroblastoma has been reported but hitherto its genetic association with cancer and effects on gliomas have not been studied." (PMID 26207917, 2015). "Previously, ZFPM2 has been found to be involved in the pathogenesis of cancers, e.g. its abnormal gene expression in sex cord-derived ovarian tumors and neuroblastoma." (PMID 26207917, 2015). "In addition, the possible association between this marker and more types of cancer need to be examined, especially for ovary tumor and neuroblastoma, where abnormal ZFPM2 expression has been reported, in order to determine the extent of specificity of the rs71305152-glioma association." (PMID 26207917, 2015). "For instance, immunohistochemistry, real-time RT-PCR, and microarray analysis showed a downregulation of ZFPM2/FOG2 in aggressive but not in favorable primary neuroblastoma." (PMID 32290321, 2020).
Infertility (3 papers, 2013 to 2023). "We found 4 genes (TUBA4A, UBQLN1, HTR2C, and ZFPM2) with at least two damaging DNMs in infertile females and these 4 genes were significantly enriched in our affected individuals compared to other control groups." (PMID 37024973, 2023).
lung adenocarcinoma (3 papers, 2018 to 2022). A carcinoma that arises from the lung and is characterized by the presence of malignant glandular epithelial cells. "Through interaction with UPF1 to promote ZFPM2 mRNA decay, ZFPM2-AS1 could promote lung adenocarcinoma (LUAD) cell growth, migration, and the epithelial-mesenchymal transition process, thus exerting oncogenic functions." (PMID 35993327, 2022). "Using the TIMER database, we hypothesized that ZFPM2 was negatively correlated with ZFPM2-AS1 expression, as well as the immune infiltration levels in lung adenocarcinoma (LUAD)." (PMID 33173620, 2020).
lung carcinoma (3 papers, 2018 to 2024). "These genes include GRIA3, TAF7L, ARL14, PCDHGA9, MDGA1, ZFPM2, OSR2, TMC8/TMC6, HCN2, and CDK5R2, which are likely to be relevant in human lung cancer and are also epigenetically deregulated upon exposure to ECS in our animal study." (PMID 39273313, 2024). "In addition, siRNA knockdown was employed to probe the functional roles of ZFPM2 and OSR2 in lung cancer cell proliferation." (PMID 39273313, 2024).
diaphragmatic hernia (2 papers, 2020 to 2021). A congenital or acquired weakness or opening in the diaphragm which allows abdominal contents to protrude into the chest cavity; congenital diaphragmatic hernias are caused when the embryonic diaphragm fails to fuse. "Concurrently, knockout mice for NR2F2 (formerly called COUP-TFII) and ZFPM2 (also known as FOG2), both modulators of RA transcriptional activity, exhibit diaphragmatic hernia and lung hypoplasia." (PMID 34831210, 2021).
Hypercholesterolemia (2 papers, 2019 to 2021). An increased concentration of cholesterol in the blood. "Previous studies have associated genetic variants of ZFPM2 with hypercholesterolemia and metabolic syndrome." (PMID 34638758, 2021). "In conclusion, these results suggest that whereas rs6993770 in ZFPM2 was positively associated with hypercholesterolemia, rs10738760 (VLDLR-KCNV2) is possibly implicated in MetS in two Middle Eastern populations." (PMID 31405227, 2019).
hypospadias (2 papers, 2016 to 2020). Hypospadias is the displacement of the urethral meatus on the ventrum of the penis. "We also observed ZFPM2 variants in three individuals with hypospadias and in some instances this was in conjunction with another DSD gene variant that had not previously been reported." (PMID 27899157, 2016). "In the case of MAP3K1, DHH, and ZFPM2 it is difficult to distinguish whether variants identified in patients categorized as isolated hypospadias expand the known mutation spectrum of these genes or whether these patients have underlying gonadal dysgenesis." (PMID 27899157, 2016).
melanoma (2 papers, 2014 to 2024). A malignant, usually aggressive tumor composed of atypical, neoplastic melanocytes. "Interestingly, several exclusively mutated genes in murine dormant cells such as ZFPM2, PRKDC, TDRD1, NES, CDC42BPBD and HX57, exhibited moderate to high frequencies of mutation in human melanoma." (PMID 39223638, 2024).
Obesity (2 papers, 2021 to 2025). Accumulation of substantial excess body fat. "Of them, Ctnnd2, Dap, Marchf6, Cmbl, Sdc2, Cpq, Stk3, Vps13b, Cox6c, Grhl2, Fzd6, Cthrc1, Lrp12, and Zfpm2 showed associations or had functions related to atherosclerosis or obesity." (PMID 40362477, 2025). "Our results showed that higher methylation in cg20707527 (ZFPM2 gene) and lower methylation in cg11445109 (CYP2E1 gene) could have a role in the stability of the healthy phenotype in obesity." (PMID 34638758, 2021).
astrocytomas (1 paper, 2015). "Based on ANOVA analysis, the expression levels of ZFPM2 were significantly different between the glioma grades (P = 0.012), and the astrocytoma subtype grades (P = 0.006), which included the most severe grade IV GBM patients." (PMID 26207917, 2015). "In the astrocytoma subtype, higher ZFPM2 expression was also correlated with the rs71305152 heterozygous genotype (P = 0.028)." (PMID 26207917, 2015). "When ANOVA was employed to compare the different grades in the individual glioma subtype, significant difference in ZFPM2 expression between grades was found for astrocytoma (P = 0.006), but not for oligodendroglial tumors where grade IV tumors are absent." (PMID 26207917, 2015).
brain tumor (1 paper, 2015). "In summary, the present study represents the first instance where effects of ZFPM2 on gliomas, the most prevalent brain tumor, and balancing selection in the gene have been examined." (PMID 26207917, 2015).
coronary artery disease (1 paper, 2016). "One of the loci for week 1 FS near Lrp12 and Zfpm2 on chromosome 15 has previously been shown in a small human GWAS to be associated with sudden cardiac arrest due to ventricular tachycardia and ventricular fibrillation in patients with coronary artery disease (p-value = 1 x 10−6)." (PMID 27385019, 2016).
dilated cardiomyopathy (1 paper, 2024). Cardiomyopathy which is characterized by dilation and contractile dysfunction of the left and right ventricles. "GATA4 is a critical regulator of cardiac differentiation; FOG2/ZFPM2 is essential for heart morphogenesis and coronary development; FOS is significantly activated in dilated cardiomyopathy." (PMID 38474301, 2024).
female infertility (1 paper, 2023). Diminished or absent ability of a female to achieve conception. "Based on previous published studies, we speculated that other three genes (UBQLN1, HTR2C, and ZFPM2) may also play a role in female infertility besides TUBA4A." (PMID 37024973, 2023).
glaucoma (1 paper, 2012). Increased pressure in the eyeball due to obstruction of the outflow of aqueous humor. "Using RT-PCR, we found that both LRP12 and ZFPM2 are expressed in the human optic nerve, as well as in other ocular tissues relevant to glaucoma." (PMID 22570617, 2012).
glioma (1 paper, 2015). A benign or malignant brain and spinal cord tumor that arises from glial cells (astrocytes, oligodendrocytes, ependymal cells). "Disease-association results showed that rs71305152 was associated with gliomas at the genotype level, suggesting that ZFPM2 represents a glioma susceptibility gene." (PMID 26207917, 2015). "Nevertheless, the P value of Hardy-Weinberg equilibrium test, which has been validated as furnishing evidence for association, was dramatically less than 0.05 in the glioma cohort (P = 0.0015), thereby supporting ZFPM2 as a glioma susceptibility gene." (PMID 26207917, 2015). "That the genotypes of ZFPM2 could be a contributing factor to the greater prevalence of gliomas in males highlights the importance of the polymorphism." (PMID 26207917, 2015). "The present results suggest that the susceptibility gene ZFPM2 could also be a contributing factor to the higher incidence of gliomas observed for males." (PMID 26207917, 2015). "Thus the selection of rs71305152, close to both AluSp and AluSx within ZFPM2, as a potential glioma susceptibility marker in the present study is consistent with the frequent location of potential regions with disease-associated alleles in the neighborhood of Alu elements." (PMID 26207917, 2015). "ZFPM2 mRNA expression was negatively correlated with the grades of gliomas (P = 0.002), with higher expression levels in the low-grade gliomas." (PMID 26207917, 2015). "When ANOVA analysis was conducted in the combined-subtype cohort, significant difference was found between ZFPM2 expression levels in the different glioma grades (P = 0.012)." (PMID 26207917, 2015). "However, there have been no genetic association studies and the significance of ZFPM2 in gliomas is unclear." (PMID 26207917, 2015). "Moreover, ZFPM2 could be a useful disease severity indicator, as its expression levels were negatively correlated with glioma grades, and summary statistics tests demonstrated that the gene is under the influence of balancing selection." (PMID 26207917, 2015). "Therefore, the genotypes appear to exert their impact on the incidence of gliomas, possibly involving ZFPM2 expression, but not the progression of glioma to severity." (PMID 26207917, 2015).
multicystic mesothelioma (1 paper, 2020). "Moreover, ZFPM2-ELF5 was identified by RNA sequencing among the fusion gene transcripts in multicystic mesothelioma, whereas a ZFPM2 microdeletion was found in a case of adult Wilms tumor." (PMID 32290321, 2020).
nasal polyp (1 paper, 2021). "Thus, the expression pattern of ZFPM2 and HMCN provides the preliminary view, and the exact role of the investigated genes in AERD nasal polyp epithelial cells requires further investigation." (PMID 34439758, 2021).
OFCD syndrome (1 paper, 2022). "Collectively, our findings suggest that BCOR mutation-induced ZFPM2 regulation via BCL6 possibly contributes to hyperactive root formation in OFCD syndrome." (PMID 35957990, 2022). "A total RNA microarray revealed alterations in the expression of numerous genes in BCOR Mut PDL cells, several of which are implicated in transcriptional upregulation; NFIB, DLX5, and ZFPM2 were the most significantly upregulated genes in OFCD syndrome." (PMID 35957990, 2022). "Our findings contribute to the current knowledge on the abnormal gene upregulation that occurs in response to the decline in the BCOR corepressor in patients with OFCD syndrome; we also show that ZFPM2 is a plausible downstream gene involved in radiculomegaly." (PMID 35957990, 2022). "In this study, we show that a BCOR mutation induced ZFPM2 regulation via BCL6, subsequently regulating ALP expression and cellular proliferation and possibly contributing to hyperactive root formation in the OFCD syndrome." (PMID 35957990, 2022). "In patients with OFCD syndrome, BCOR regulates ZFPM2, which in turn regulates ALP expression during tooth root elongation." (PMID 35957990, 2022). "Our findings suggest that BCOR failed to repress its downstream genes, resulting in elevated ZFPM2 and ALP expression and subsequent upregulation of cell proliferation, ultimately leading to hyperactive root formation in OFCD syndrome." (PMID 35957990, 2022).
osteoporosis (1 paper, 2021). A condition of reduced bone mass, with decreased cortical thickness and a decrease in the number and size of the trabeculae of cancellous bone (but normal chemical composition), resulting in increased fracture incidence. "Compared with the control group, HIST1H3G, NOP2, OXA1L, and ZFPM2 were upregulated in osteoporosis, and MAP3K5 was downregulated." (PMID 33778083, 2021).
Pallister Killian syndrome (1 paper, 2014). "Among the differentially expressed genes, we identified several genes whose misexpression may be associated with the clinical phenotype of Pallister Killian syndrome such as downregulation of ZFPM2, GATA6 and SOX9, and overexpression of IGFBP2." (PMID 25329894, 2014).